INS (insulin)
Diseases named in the same sentence as INS in open-access papers (continued):
Sharing a sentence is not in itself a finding about the gene and the disease.
Glucose intolerance (continued). "These include: smaller size of β-cells, diminished insulin content in pancreas, hypoinsulinemia, glucose intolerance, as well as smaller CSA of myofibers and reduced content of muscle PCr [and this work]." (PMID 19479038, 2009). "With regard to these last parameters, it is known that calcium per se is important for insulin secretion, as well as for correction of glucose intolerance." (PMID 18638371, 2008). "Insulin sensitizers have proven to be beneficial only in obese women (BMI > 35 kg/m2 ) with glucose intolerance." (PMID 19562048, 2008). "It has also been demonstrated that these changes in the secretion of serum insulin precursor peptides occur incrementally as glucose intolerance deteriorates." (PMID 18516349, 2008). "The metabolic activity of visceral fat can increase free fatty acid circulation, decrease insulin uptake by the liver, increase circulating insulin levels, and ultimately lead to glucose intolerance." (PMID 18793503, 2008). "Kir6.2- or SUR1-knockout (KO) mice show insulin hypersecretion immediately after birth, but rapidly and unexpectedly progress to glucose intolerance and insulin hyposecretion as adults." (PMID 18959471, 2008). "Metformin was effective only in those patients who had high fasting insulin levels and glucose intolerance and were able to lose weight only when on metformin." (PMID 19562048, 2008). "Levels of glucose intolerance, central obesity (as measured by waist to hip ratio), fasting triglyceride, and insulin are uniformly elevated in South Asians compared to Europeans." (PMID 17678547, 2007). "Mice in this studydeveloped insulin and glucose intolerance with age, and exhibitedseverely compromised insulin-stimulated muscle glucose uptake, aswell as liver and adipose tissue IR." (PMID 17389768, 2007). "Several animal models have shown that muscle fiber-type transformation is associated with a shift in the metabolic parameters to a more insulin-responsive phenotype and protects against the development of diet-induced glucose intolerance." (PMID 17767910, 2007). "The liver-specific STAT3 knockout mouse is insulin resistant and develops glucose intolerance when fed a high-fat diet, due in part to increased expression of PCK1 and G6P." (PMID 15985155, 2005). "In fact, we had previously reported increased insulin levels in subsets of this population with elevated body mass index, hypertension, or glucose intolerance, which are insulin-resistant states." (PMID 12462278, 2002). "In addition, the insulin peak during OGTT was delayed in pwCF NGT and further delayed in pwCF GI, suggesting that glucose intolerance in CF is mainly driven by a right-shifted insulin response." (PMID 41489009, 2026). "AT-Sdc4 deficiency significantly alleviated HFD-induced glucose intolerance in mice, while there were no significant changes in insulin sensitivity among the four mouse groups." (PMID 40180176, 2025). "This glycemic profile is characteristic of glucose intolerance and may reflect reduced insulin sensitivity." (PMID 41227339, 2025). "While R. torques administration modestly alleviated glucose intolerance in Se-deficient mice, it did not affect insulin resistance or fasting glucose levels." (PMID 41255977, 2025). "Fbln5 deletion in β-cells caused slight glucose intolerance in βFbln5KO mice at 3 and 12 weeks of age without impaired insulin secretion." (PMID 39995864, 2025). "However, at 9-months of age, thymectomized mice exhibited greater overall body mass, glucose intolerance, and greater fasting insulin." (PMID 41034932, 2025). "Additional progesterone and prolactin from the placenta in a pregnancy state could lead to glucose intolerance by inhibiting insulin action resulting in GDM." (PMID 41013820, 2025). "Inhibition of TRPC3, whether through pharmacologic inhibition or knockout, results in decreased insulin secretion and glucose intolerance in mice." (PMID 40316897, 2025).
Glucose intolerance (continued). "In vitro and in vivo studies have shown that myocytes that contain mitochondria-enriched extracellular vesicles exposed to pathogenetic conditions negatively demonstrated impaired insulin signaling and insulin-stimulated glucose uptake, developing further glucose intolerance." (PMID 40507468, 2025). "PAK1 plays an unforeseen and beneficial role in beta cells by promoting insulin biogenesis via enhancing the expression of PDX1, NEUROD1 and INS, along with anti-apoptotic effects, that culminate in increased insulin content and beta cell mass in vivo and ameliorate diet-induced glucose intolerance." (PMID 39404845, 2025). "Together, these data suggest that FGF21 and GDF15 act synergistically to improve glucose homeostasis and insulin sensitivity in OPA1 BKO male mice, with their combined absence resulting in glucose intolerance and prevention of improvement in insulin sensitivity." (PMID 40897647, 2025). "Additionally, increased PPARα activity resulting from STAT6 silencing inhibits insulin’s anabolic effects, leading to glucose intolerance." (PMID 41007770, 2025). "Evidence from Neu1-deficient mice shows impaired insulin sensitivity and glucose intolerance without significant changes in insulin production, suggesting that NEU1 primarily affects insulin action rather than secretion." (PMID 41301440, 2025). "Cur improves HFD-induced glucose intolerance, enhances insulin sensitivity, and alleviates LMD." (PMID 41375947, 2025). "Another study revealed that the ablation of the β1 integrin receptor in pancreatic β-cells inhibited the expression of cell cycle-regulating genes and β-cell expansion without causing glucose intolerance or reducing insulin secretion in response to glucose." (PMID 39995864, 2025). "While it is widely acknowledged that exercise can delay the progression of glucose intolerance by enhancing insulin secretion and improving maternal outcomes for women with GDM, few studies have specifically investigated the association between exercise and adverse neonatal outcomes." (PMID 40235647, 2025). "Insulin signaling is interfered with by this inflammation, which makes glucose intolerance worse." (PMID 40565268, 2025). "Conversely, frequent and intermittent rapamycin-treated mice had impaired glucose tolerance and insulin sensitivity compared to vehicle-treated mice after PoWeR; however, intermittent rapamycin reduced the impact on glucose intolerance versus frequent rapamycin." (PMID 40704394, 2025). "In addition, inactivation of insulin or insulin-like growth factor-1 receptors in the central amygdala and hippocampus results in cognitive impairment, anxiety-like behavior, and glucose intolerance in mice." (PMID 40379890, 2025). "Furthermore, the increase in fat mass in HFD mice was also accompanied by glucose intolerance and higher insulin and leptin plasma concentrations compared to SD mice." (PMID 40001261, 2025). "Elevated hepatic IGFBP1 may have neutralized IGF-1 in the livers of Cnot4 Het mice, leading to hepatic insulin resistance and inhibition of glucose uptake, and eventually augmenting glucose intolerance in Cnot4 Het mice." (PMID 40424271, 2025). "However, excessive accumulation of d-Ser can impair insulin secretion and lead to glucose intolerance." (PMID 40680136, 2025). "A study using a DMPK gene knockout (dmpk−/−) mouse model revealed that dmpk−/− mice exhibited impaired insulin signaling, glucose intolerance, and reduced insulin-dependent GLUT4 transport in muscle tissue, a phenomenon not observed in fat and liver tissues, which do not express DMPK." (PMID 41018201, 2025). "However, the OGTT test in this study revealed glucose intolerance despite of high level of insulin presence in the plasma of HF diet-fed rats." (PMID 40168333, 2025). "It binds the insulin gene promoter, facilitating its transcription in response to varying glucose levels and loss or mutations of PDX1 are known to impair this process causing glucose intolerance." (PMID 41199860, 2025).
Glucose intolerance (continued). "Similarly, disruption of mTORC2 in various tissues, including adipose tissue, brain, pancreatic islets, and skeletal muscle, leads to glucose intolerance and impaired insulin sensitivity." (PMID 39996055, 2025). "The participants on oral medication had 4.22 times higher odds of having postpartum glucose intolerance (a0R=4.22, 95% CI=1.74-10.23, P=0.001), while those on a combination of oral medication and insulin exhibited 14.22 times higher odds (a0R=14.22, 95% CI= 1.81—111.39, P=0.012)." (PMID 41523956, 2025). "In contrast to the Aspg LKO mice, mice overexpressing Aspg in livers demonstrated the opposite phenotypes as visualized by more glucose intolerance, higher postprandial blood glucose levels and lower insulin levels than the control group (WT + AAV8-ASPG versus WT + AAV8-VEC)." (PMID 40760121, 2025). "Thus, deletion of CerS2, either systemically or selectively in the pancreatic β-cell, to limit the production of very long ceramide chains, lowers the insulin content of pancreatic islets and impairs glucose intolerance on both normal and high fat diet." (PMID 40463068, 2025). "With no changes in resting glucose and pancreatic morphology in CBD-exposed offspring, we next examined if alterations in peripheral insulin-target organs might account for the glucose intolerance observed." (PMID 37855335, 2024). "In addition, however, various “indirect weight-dependant mechanisms” have been proposed, the most studied of which are glucose intolerance, insulin and leptin resistance." (PMID 38542217, 2024). "Another study also indicated that serotonin could also act via the 5-HTR3A Na-K-selective ion channel receptor to promote insulin exocytosis, and mice deficient for 5-HTR3A developed glucose intolerance during pregnancy." (PMID 38907293, 2024). "In preclinical models of Lepdb/+ pregnant mice, administration of quinoa protein hydrolysate alleviated glucose intolerance, improved liver insulin signaling, and several peptides exhibited anti-dipeptidyl peptidase-4 (DPP-IV) activity, a key enzyme involved in blood glucose control." (PMID 39061898, 2024). "However, it manifested as glucose intolerance, insulin immaturity, and a noteworthy reduction in glucose‐stimulated insulin secretion (GSIS)." (PMID 39297407, 2024). "Most importantly, treatment with H4CBD mitigated the dynamic, strain-associated glucose intolerance independent of static enhancements of proteins of the insulin signaling pathway." (PMID 37899754, 2024). "Interestingly, loss of BBS1 in POMC neurons led to glucose intolerance and insulin insensitivity, whereas BBS3 deficiency in these neurons is associated with slight impairment in glucose handling, but normal insulin sensitivity." (PMID 38223458, 2024). "Indeed, GDM is usually diagnosed in the second trimester, when pregnant women already show glucose intolerance and elevated plasma insulin levels as indicated by HOMA-IR assessment." (PMID 38791090, 2024). "However, the OD group was characterized by glucose intolerance, increased insulin requirements, and decreased insulin sensitivity." (PMID 39474247, 2024). "Furthermore, the introduction of an anti-IL-17 antibody to insulin-resistant mice induced by angiotensin II resulted in enhanced insulin sensitivity and reduced glucose intolerance." (PMID 39606781, 2024). "Additionally, 2’FL supplementation reduced glucose intolerance, as evidenced by the shape of the glycaemia curve during the oral glucose tolerance test and by the lower insulin levels in fasting state." (PMID 38740509, 2024). "Β-cell-specific Hif1a knockout mice exhibit impaired insulin secretion and glucose intolerance." (PMID 38673770, 2024). "Notably, EC senescence models based on TRF2 inactivation displayed a slightly different phenotype: elevated blood insulin and glucose intolerance, which developed in older mice even on regular diet." (PMID 38475941, 2024).
Glucose intolerance (continued). "Detailed observations of insulin secretion in previous reports revealed that the reduction of the IdIR ratio to the insulin secretory response to intravenous glucose loading along with glucose intolerance is more prominent in Caucasians than in Japanese subjects." (PMID 38966210, 2024). "Furthermore, IPGTT and ITT experiments indicated that Fmo3 knockdown improved fasting blood glucose, glucose intolerance, and insulin sensitivity in db/db mice." (PMID 38514666, 2024). "Furthermore, the functional relevance of L- arginine in T2DM has been shown to improve insulin sensitivity, glucose disposal and reduce glucose intolerance." (PMID 38355488, 2024). "This separation of body weight and fat mass from insulin and glucose intolerance is unique." (PMID 39608054, 2024). "However, to more deeply understand the etiology of glucose intolerance, future work can include targeted studies of insulin signaling including insulin tolerance testing and/or metabolic clamp studies." (PMID 37935884, 2024). "The pathogenesis of hypovitaminosis D-induced T2DM is possibly due to the hereditary variations in vitamin D receptors and vitamin D-binding protein genes, which lead to a state of glucose intolerance that subsequently alters the synthesis and secretion of insulin finally ending up in T2DM." (PMID 39544568, 2024). "Additionally, raised levels of FFAs, especially saturated FFAs (e.g., stearic and palmitic acid) in plasma, impair insulin secretion and sensitivity and promote glucose intolerance." (PMID 39092382, 2024). "In β-cell METTL14 knockout mouse lines, glucose intolerance, decreased insulin secretion and lower body weight could be observed." (PMID 39296713, 2024). "Consistent with the decrease in fasting glucose levels, the DJB group showed a significant improvement in glucose intolerance with increased responses of insulin, GLP-1, and GLP-2 secretion during OGTT, as well as improved insulin intolerance 6 weeks postsurgery." (PMID 39263491, 2024). "Likewise, male and female study participants exposed to IH show altered insulin sensitivity and glucose intolerance." (PMID 38542217, 2024). "In addition, LPCAT3 overexpression in skeletal muscle impairs insulin signaling and aggravates glucose intolerance." (PMID 38519981, 2024). "However, after four weeks of HFD feeding, S1P2−/− mice exhibited much smaller adipocytes with improved glucose intolerance/insulin sensitivity, accompanied by reduced crown-like structures and improved M1/M2 macrophage polarization in adipose tissue sections." (PMID 38256005, 2024). "Furthermore, mice fed the HFHS diet demonstrated significantly increased glucose intolerance and insulin levels compared to those fed a normal diet." (PMID 39139961, 2024). "Previous epidemiological data have observed that subjects who present high plasma insulin levels show both a disturbance in blood pressure and altered peripheral insulin sensitivity (commonly glucose intolerance) compared to healthy subjects (normoinsulinic and normotensive)." (PMID 39273236, 2024). "Also, glucose intolerance appeared in Htr3a knockout mice during pregnancy, and insulin secretion was increased in pancreatic islets by treatment with an Htr3 agonist and decreased by an Htr3 antagonist." (PMID 38999937, 2024). "Thus, in the choline diet-fed C57BL/6 J mice, glucose intolerance resulted from inadequate insulin secretion instead of insulin resistance." (PMID 38514666, 2024). "Thus, the high-fat diet promotes glucose intolerance and impaired insulin signaling, results that are maintained with treatment with CCl4." (PMID 38660995, 2024). "Notably, injection of IL-10-treated SVFs induced Akt phosphorylation in the livers of Leprdb/db mice following insulin administration and reduced glucose intolerance." (PMID 39125659, 2024). "Moreover, the high-fat diet was able to promote glucose intolerance and decrease the protein activity of the insulin pathway." (PMID 38660995, 2024).
Glucose intolerance (continued). "WTAP-betaKO mice displayed severe glucose intolerance and reduction in pancreatic insulin content." (PMID 39296713, 2024). "We studied β-cell GHSR deficiency under DIO and aging and found that β-cell GHSR deficiency did not significantly alter insulin secretion or glucose intolerance." (PMID 38794702, 2024). "Furthermore, the levels of INS and ADPN were both decreased in the D7 groups, indicating that inadequate secretion of these hormones was the primary cause of glucose intolerance in carnivorous fish species." (PMID 38668364, 2024). "To assess whether the glucose intolerance is due in part to altered insulin sensitivity in peripheral tissues, we performed ITT in male and female mice of 7–10 weeks of age." (PMID 38393018, 2024). "Conversely, enhanced glucose intolerance and insulin levels were reduced after MRP supplementation." (PMID 39139961, 2024). "We hypothesised that insulin sensitivity and the disposition index, which is the product of insulin secretion and insulin sensitivity, worsen with progression in glucose intolerance in CF." (PMID 39093413, 2024). "Similarly, humans exposed to high levels of synthetic and endogenous glucocorticoids when developing in utero presented glucose intolerance and low insulin secretion." (PMID 39765703, 2024). "Another study has shown that for T2DM mice, supplementing with the Bifidobacterium longum NBM7-1 and Lactiplantibacillus rhamnosus NBM17-4 alleviates glucose intolerance through the upregulation of IL-22, which enhances insulin sensitivity and pancreatic functions while reducing liver steatosis." (PMID 39062940, 2024). "Our work as well as that of others suggests that increased hepatic DNL from a high carbohydrate diet during chronic positive energy balance may protect from some of the effects of ectopic lipid deposition on insulin sensitivity and glucose intolerance." (PMID 39490929, 2024). "Consistent with this hypothesis, we show that β cell–specific depletion of SUCNR1 in mice leads to an aberrant metabolic phenotype characterized by increased glucose intolerance and defects in insulin secretion under HFD feeding." (PMID 38713514, 2024). "This suggests that glucose intolerance is predominantly associated with reduced muscle glucose uptake without affecting hepatic insulin sensitivity in CF as previously indicated." (PMID 39093413, 2024). "In addition, humans exposed to high levels of dexamethasone or cortisol during fetal life have glucose intolerance and a reduced ability of the pancreas to secrete insulin, in addition to other metabolic dysfunctions." (PMID 39765703, 2024). "Another explanation may be attributed to the high dose of gestational hormones administered with IVF techniques, which may precipitate metabolic derangements, insulin resistance, and glucose intolerance." (PMID 38594776, 2024). "Furthermore, treating mice with an SphK inhibitor induces glucose intolerance and decreases plasma insulin levels." (PMID 38256005, 2024). "The authors created a mouse line where Tmem30a was knocked out specifically in pancreatic β cells and found that the mice exhibited glucose intolerance that worsened with age, abnormally large islets with increased beta cell mass, and hyperglycemia with impaired glucose-stimulated insulin secretion." (PMID 38382846, 2024). "The insensitivity of peripheral cells characterises glucose intolerance to insulin action." (PMID 38203195, 2023). "These correlations are consistent with the roles of unsaturated long-chain 2-MAGs including 2-AG, 2-DPG, and 2-DHG, as they may increase insulin sensitivity and decrease glucose intolerance through activation of CB2, TRPV1, and other targets." (PMID 36774515, 2023). "It has also been observed that long-term treatment with mTOR-Is (20 weeks) partially restored the detrimental effects on metabolism with enhanced insulin sensitivity, increased oxygen consumption, and improved serum lipid profile with a certain degree of glucose intolerance." (PMID 37250653, 2023).